BAP1 (BRCA1 associated deubiquitinase 1)
Diseases named in the same sentence as BAP1 in open-access papers (continued):
Sharing a sentence is not in itself a finding about the gene and the disease.
mesothelioma (continued). "However, BAP1 immunostaining demonstrated nuclear loss and p16-FISH demonstrated homogenous deletion in tumor cells, confirming a diagnosis of mesothelioma." (PMID 39006698, 2024). "In addition, KEGG pathway enrichment analysis of genes deregulated in mesothelioma in which Bap1 was disrupted revealed an overall prevalence of genes implicated in PI3K-Akt and MAPK signalling among others." (PMID 38054839, 2024). "In addition, the BRCA1-associated protein 1 (BAP1) gene has been found to be mutated, deleted or epigenetically silenced in human mesothelioma." (PMID 38519707, 2024). "In addition to the high sensitivity of BAP1-mutant mesothelioma, we show that the treatment of EZH2 inhibitor in conjunction with FGFR inhibitor is effective in uveal melanoma as well." (PMID 38054839, 2024). "Inversely BAP1 expression was found to increase the effect of gemcitabine in mesothelioma cell lines, showing that the expression of BAP1 may affect outcomes differently according to type of chemotherapy." (PMID 38280040, 2024). "Wildtype BAP1 has been associated with sensitivity to gemcitabine treatment in mesothelioma cell lines, but this has not been validated in patients with PeM." (PMID 38642130, 2024). "Finally, in the Ramucirumab Mesothelioma clinical trial (RAMES), mutation of the BAP1 gene was associated with a prolonged median progression-free survival (mPFS) in those patients treated with platinum/pemetrexed regimens (p = 0.04)." (PMID 38673021, 2024). "These variations can be explained by the fact that our mouse mesothelioma cell lines are genetically similar except for their Bap1 status whereas the human tumour-derived cell lines have co-mutations which might affect the efficacy of the combinations." (PMID 38519707, 2024). "Given preclinical data demonstrating the antitumor activity of EZH2 inhibition in BAP1 mutant mesothelioma, a phase 2 clinical trial evaluated the safety and efficacy of tazemetostat, a selective oral EZH2 inhibitor, in patients with relapsed or refractory MPM (NCT02860286)." (PMID 38610930, 2024). "However, our observations in this study suggested in BAP1 frequently altered malignancies, such as renal cancer, mesothelioma and pancreatic cancer, manipulating the expression of BAP1 have limited effect on the expression of PD-L1 of the tumor cells." (PMID 39350280, 2024). "The U.S. National Cancer Institute (NCI) has opened two clinical trials to prospectively study frequency of mesotheliomas and other cancers in individuals with BAP1 GPV, which may address some of these questions." (PMID 37607989, 2023). "Moreover, this elevated PRC2 occupancy in BAP1-altered mesothelioma creates selective sensitivity to PRC2 inhibitors." (PMID 36657447, 2023). "Exploiting this vulnerability pharmacologically, we show that mesothelioma cells lacking BAP1 are more susceptible to the mevalonate pathway inhibitor zoledronic acid (ZA), identifying another Bap1-loss-specific vulnerability." (PMID 36657447, 2023). "A pilot study of chemotherapy treatment using previously published doses, revealed CNP mice to be extremely sensitive to chemotherapy-induced toxicity, requiring reduction of both drugs to half the concentrations used in mesothelioma mouse model driven by triple deletion of Bap1, Cdkn2a and Nf2." (PMID 37441092, 2023). "Hence, BAP1 and BRCA1 are both essential for accurate mitotic progression of mesothelioma cells with the role of BAP1 likely explained in part by its regulation of BRCA1 expression." (PMID 36550359, 2023). "Moreover, loss of expression of BAP1 and BRCA1 proteins is strongly correlated in tumour samples taken from mesothelioma patients." (PMID 36550359, 2023). "We experienced an excellent value of the “two-hits” panel of Claudin-4 and BAP1 in the differential diagnosis between mesothelioma with epithelioid features and conventional metastatic carcinomas, demonstrating a 94% sensitivity, a 100% specificity and a 96% diagnostic accuracy." (PMID 36673059, 2023).
mesothelioma (continued). "Future studies on understanding the key role of BAP1 in tumors, especially in mesothelioma, could lead to the development of novel therapies with substantial clinical improvements." (PMID 37626858, 2023). "CRISPR-Cas9 was used to create mesothelioma cell lines that lack BAP1." (PMID 37469419, 2023). "Since the loss of BAP1 and MTAP immunostaining is indicative of a malignant transformation in mesothelial cells and is frequently found in mesothelioma with an epithelioid component, several studies investigated the diagnostic role of these markers, even in its sarcomatous counterpart." (PMID 36673059, 2023). "Our data revealed that depletion of BAP1 leads to loss of BRCA1 protein expression in mesothelioma-derived cell lines but not vice versa." (PMID 36550359, 2023). "Based on the excellent sensitivity and specificity of this simple “double-hit” (Claudin-4 and BAP1) panel for discriminating mesothelioma with epithelioid features from conventional carcinoma, we replicated the same study design in the setting of sarcomatoid neoplasms, namely SM versus SC." (PMID 36673059, 2023). "BAP1 mutant mesothelioma tumors have a poor prognosis and few therapeutic options." (PMID 36657447, 2023). "BAP1 is an oncosuppressor protein that acts as a deubiquitinase and is involved in gene expression and chromatin regulation; it is commonly inactivated in mesotheliomas." (PMID 36980631, 2023). "BAP1 and CDKN2A are the most common inactivating mutations in mesothelioma." (PMID 37880686, 2023). "The significantly earlier onset of mesothelioma in patients with BAP1 TPS may also be a factor in the better clinical outcomes seen for these patients." (PMID 38015374, 2023). "The critical role of BAP1 in the pathogenesis of mesothelioma is underscored by the finding that over 60% of sporadic—not genetically related—mesotheliomas carry biallelic inactivating BAP1 mutations." (PMID 37880686, 2023). "However, TG2-179-1 kills both BAP1-insensitive and BAP1-depleted colon cancer cells as well as BAP1-null mesothelioma and ccRCC cells, indicating that TG2-179-1 targets BAP1 as well as other cellular proteins." (PMID 36754982, 2023). "With the lack of efficient targeted therapy for mesothelioma and kinase inhibition being one of the most pharmacologically tractable therapeutic strategies, we performed a dropout screen against kinases in Bap1-proficient and -deficient settings." (PMID 36657447, 2023). "Before setting out to explore how loss of BAP1 might regulate mitotic events in mesothelioma, we wished to examine the interdependence of BAP1 and BRCA1 protein expression in mesothelioma cells by Western blot." (PMID 36550359, 2023). "IHC staining of mesothelioma related markers including BAP1, EMA, Thrombomodulin (CD141), WT1, Podoplanin (D2-40), Calretinin and Cytokeratin6 (CK-6) revealed increased protein expression in 2175, 1187 or 1157 3D spheroids when compared to their 2D counterparts." (PMID 36091141, 2022). "Nonetheless, only a few genetic markers are known, including YAP activity and altered BAP1 expression, and their role in mesothelioma formation and maintenance remains unclear." (PMID 35354817, 2022). "BAP1 expression is frequently lost in mesothelioma, UM, and RCC due to somatic inactivation." (PMID 35885614, 2022). "Of note, ADAR2 expression levels are higher in mesothelioma cell lines with wt BAP1." (PMID 36221913, 2022).
mesothelioma (continued). "Germline mutations in the tumor suppressor gene BRCA1-associated protein-1 (BAP1) lead to BAP1 tumor predisposition syndrome (BAP1-TPDS), characterized by high susceptibility to several tumor types, chiefly melanoma, mesothelioma, renal cell carcinoma, and basal cell carcinoma." (PMID 35885614, 2022). "Another single-arm phase II trial investigated tumor response of olaparib in refractory mesothelioma with or without germline or somatic BAP1 mutation (NCT03531840)." (PMID 36362209, 2022). "Although not investigated, this may correspond to differences in tumour growth seen in mesothelioma mouse models where co-alterations of BAP1, NF2 and CDKN2A/B led to a faster tumour growth compared to tumours with alterations in only one or two genes." (PMID 36138075, 2022). "In 2011, the team conducted a study in two families in the United States who had not been exposed to asbestos; they found that the BAP1 mutation was associated with a high incidence of mesothelioma." (PMID 34641979, 2021). "Since we observed strong H3K27me3 (histone H3 lysine 27 trimetylation) immunoreactivity in BAP1 wild-type mesothelioma biopsies, we decided to characterize in vitro the response/resistance of BAP1 wild-type mesothelioma cells to the EZH2 selective inhibitor, EPZ-6438." (PMID 34277422, 2021). "Furthermore, Bap1(+\-) mice develop mesothelioma after exposure to doses of asbestos fibers that are unlikely to induce mesothelioma in wt mice." (PMID 34235080, 2021). "Similar mechanisms are implicated in the tumor suppressor activities of BAP1 in mesothelioma, but not in uveal melanoma cell lines." (PMID 33912157, 2021). "As the most frequent mutations/deletions, the collaborative inactivation of BAP1, NF2, and CDKN2A could result in rapid and aggressive mesothelioma, while homozygous mutation rarely results in carcinogenesis." (PMID 34299035, 2021). "However, while Bap1(+\-) mice develop mesothelioma, they also develop other cancers such as uveal and cutaneous melanoma." (PMID 34235080, 2021). "Molecular genetic analysis of mesothelioma revealed frequent copy number loss and recurrent somatic mutations in TSGs such as BRCA1-associated protein 1 (BAP1, 60% of the cases), neurofibromin 2 (NF2, 75% of the cases), and cyclin-dependent kinase inhibitor 2A (CDKN2A, 60% of the cases)." (PMID 34299035, 2021). "Germline defects of BAP1 are responsible for the BAP1-tumor predisposition syndrome (BAP1-TPDS) including the occurrence of renal cell carcinoma, uveal melanoma, cholangiocarcinoma and mesothelioma." (PMID 34249695, 2021). "However, previous studies of UM and mesothelioma cells have shown that BAP1 inactivation increases sensitivity to HDAC inhibitors and reprograms their stemness." (PMID 34453044, 2021). "Mesothelioma incidence in Bap1(+\-) mice ranged between 36-60% depending on asbestos doses." (PMID 34235080, 2021). "Mesotheliomas harboring BAP1 aberrations are characterized by elevated immune signaling and inflammatory tumor microenvironment, and, therefore, may predict long-term responses with ICPi." (PMID 33777745, 2021). "BAP1 downregulation increases the sensitivity to HDACi in mesothelioma cell lines, and therefore, it would be important to see whether BAP1 aberrations modulate response to vorinostat in VANTAGE 014 study." (PMID 33777745, 2021). "Germline mutations of BAP1 are associated with an autosomal dominant, novel cancer syndrome characterized by atypical Spitz tumors (AST), uveal melanoma, mesothelioma (MM), clear cell renal cell carcinoma, cutaneous melanoma (CM), and basal cell carcinoma (BCC)." (PMID 33541411, 2021). "In several studies, the loss of BAP1 by IHC and the homozygous deletion of p16 by FISH is very specific for mesothelioma but still may lack sensitivity to a certain extent." (PMID 33014860, 2020). "Another issue is that most mesotheliomas of peritoneal origin do show a loss of BAP1 by IHC but do not show loss of p16 by FISH." (PMID 33014860, 2020).
mesothelioma (continued). "In addition, research on mesothelioma genome supports the role of inactivated tumor suppressor genes encoded by cyclin-dependent kinase inhibitor 2A (CDKN2A), BRCA1 associated protein 1 (BAP1) and neurofibromin 2 (NF2)." (PMID 32050546, 2020). "BRCA1-associated protein 1 (BAP1) is a deubiquitinating enzyme that has long beenconsidered to be a tumor suppressor in various tumors, including renal cellcarcinoma, uveal melanoma, mesothelioma, and cutaneous melanoma." (PMID 32422649, 2020). "In BAP1 low expression mesothelioma, homozygous deletion was recognized in 76% of samples with fluorescence in situ hybridization (FISH), so there might be a considerable number of deletions that we could not detect by DNA sequencing." (PMID 30395583, 2018). "Furthermore, the most recent analysis of mesothelioma samples (TCGA-MPM) suggests up to 57% of samples with alterations in BAP1, collectively confirming that BAP1 is the most frequently altered gene in mesothelioma." (PMID 30060501, 2018). "Furthermore, arecent analysis of human mesothelioma cells also points to a role of BAP1 andthe PR-DUB complex in mitochondrial function and ROS homeostasis." (PMID 29995890, 2018). "Recently, various mutations of BAP1 have been found in several tumors, including uveal melanoma (UM), mesothelioma, renal cell carcinoma (RCC), and intrahepatic cholangiocarcinoma (ICC), but the frequency of BAP1 mutations varies widely among different tumor types." (PMID 30395583, 2018). "Our study therefore suggests that in the absence of a family history of cancers such as mesothelioma, or meningioma, the presence of histological changes described in BAP1 mutated families is a poor predictor of a germline BAP1 mutation." (PMID 28062663, 2017). "Indeed, in a BAP1(+/−) mouse model, intraperitoneal exposure to low-dose asbestos fibers showed higher levels of pro-tumorigenic M2 macrophages and incidence of mesothelioma than in wild-type littermates." (PMID 28229253, 2017). "Germline BAP1 mutations also can increase the incidence of mesothelioma; however, the BAP1 test is not generally performed, and studies on BAP1 mutations have not yet been conducted in South Korea." (PMID 28817672, 2017). "Importantly, Ino80 levels are often reduced in BAP1-null mesothelioma cells, which lack a BAP1-mediated Ino80 stabilization mechanism, and downregulated in BAP1-defective cancer cells in mesothelioma patients." (PMID 29383140, 2017). "Indeed we find that HDAC2 appears more important than HDAC1 in maintaining viability of the BAP1 positive mesothelioma cell line MSTO-211H." (PMID 25970771, 2015). "BAP1 analysed in individuals and families with CM and/or UM and mesothelioma." (PMID 25803691, 2015). "Germline BAP1 mutation carriers have an exceptionally high incidence of malignancies, including mesothelioma and uveal melanoma whereas family members who do not carry these mutations do not develop these malignancies." (PMID 26202904, 2015). "As loss of BAP1 function is implicated in a high proportion of mesothelioma, we next asked whether we could recapitulate this effect in MSTO-211H cells, which were derived from a grade 4 biphasic mesothelioma and retain wild-type BAP1 expression." (PMID 25970771, 2015). "As BAP1 depletion had a profound effect on the HDAC2/HDAC1 expression ratio in MSTO-211H cells, we next examined the relationship between endogenous HDAC2 and BAP1 mutation status in a panel of established mesothelioma cell lines." (PMID 25970771, 2015).
mesothelioma (continued). "Given that these primary cultures and patient derived tumor xenograft models recapitulate phenotypic and genetic features of the original primary mesotheliomas, they should prove useful for preclinical studies of novel drug regimens and for functional studies of BAP1 biology in mesothelioma." (PMID 25952750, 2015). "And fourth, germline mutations in nuclear deubiquitinase BRCA1-associated protein 1 (BAP1) have been observed in familial clusters of mesothelioma not necessarily linked to asbestos and in a fraction of pleural mesotheliomas in other case series." (PMID 24910640, 2014). "Although mutations in these genes have been reported in other cancer types such as glioblastoma and mesothelioma, BAP1, IDH1 and IDH2 have not been previously linked to HCC." (PMID 25159915, 2014). "About 70–80% of mesothelioma specimens possess deficiency in the INK4A/ARF locus containing p16 INK4A and p14 ARF genes, about 40% in neurofibromatosis type 2 gene (NF2) and about 10% in BRCA1 associated protein-1 (BAP1) gene." (PMID 23484132, 2013). "Testa and colleagues investigated BAP1 mutations in two American families presenting with mesothelioma and who had no contact with any of the known environmental risk factors for this disease." (PMID 23977234, 2013). "Among our families, there were three individuals with lung cancer (not mesotheliomas), two of whom carried documented BAP1 mutations." (PMID 22545102, 2012). "Germline mutations in BAP1 result in an autosomal dominant tumour predisposition syndrome that is associated with a high risk of developing various tumours, including BIMT, cutaneous melanoma, uveal melanoma, mesothelioma, renal cell carcinoma, lung adenocarcinoma and meningioma." (PMID 39268598, 2025). "Based on those findings, some investigators have concluded that germline mutations of certain cancer predisposition genes, such as Bap1, are powerful and may cause mesothelioma without environmental asbestos exposure." (PMID 40867321, 2025). "Following disease progression, molecular markers (e.g., BAP1 status) should be evaluated, and consideration should be given to anti-angiogenic agents (e.g., bevacizumab) or targeted therapies (per the 2025 Clinical Practice Guidelines for Histopathological Diagnosis of Mesothelioma)." (PMID 41395612, 2025). "Thus, we cannot conclude that germline Bap1-mutant mice have a significantly increased risk of mesothelioma in the absence of environmental exposure." (PMID 40867321, 2025). "However, given that even trace amounts of asbestos induce a high incidence of mesothelioma in Bap1-mutant mice compared to WT mice, this suggests that germline Bap1 mutations create a highly susceptible setting for a gene-environment interaction with deadly consequences." (PMID 40867321, 2025). "To statistically assess whether the proportion of mesothelioma occurrences differs between the Bap1-mutant and WT groups, we first conducted a Fisher’s exact test, which is particularly suitable for small sample sizes and instances where expected frequencies are low." (PMID 40867321, 2025). "Interestingly, the WHO grading system showed a significant prognostic role in mesotheliomas with BAP1 loss (median survival 18.7 vs. 10.4 mo, p < 0.0001) but not in cases with retained BAP1 expression (8.9 vs. 6.2 mo, p = 0.061)." (PMID 38673021, 2024). "In these cases, immunohistochemistry may be helpful in showing the presence of BRCA1-associated protein 1 (BAP-1) and demonstrating a lack of expression in the sarcomatoid mesothelioma region." (PMID 38938650, 2024). "Furthermore, BAP1 status in mesothelioma patients might be an important predictor of response to microtubule poisons that interfere with mitotic spindle assembly, as well as mediators of the DNA damage response." (PMID 36550359, 2023). "Finally, it will be important to examine whether the mitotic consequences observed in mesothelioma also occur in other cancer types, such as uveal melanomas, that lack functional BAP1." (PMID 36550359, 2023).